POTEE (POTE ankyrin domain family member E)
Synonyms: POTE-2; A26C1A; POTE2; A26C1; POTE2gamma; CT104.2
Tractability: PROTAC: ubiquitination databases record sites on it.
Gene: Protein-coding gene on chromosome 2 (131,209,536 to 131,265,278, forward strand). Ensembl gene ENSG00000188219.
Pathways (Reactome):
Signal Transduction: RHOF GTPase cycle
Gene Ontology:
Molecular function: protein binding; protein kinase binding; structural constituent of postsynaptic actin cytoskeleton
Biological process: substantia nigra development; axonogenesis; cell motility; postsynaptic actin cytoskeleton organization
Cellular component: blood microparticle; extracellular exosome; extracellular region; actin cytoskeleton; actin filament; axon; cytoplasm; membrane; NuA4 histone acetyltransferase complex; synapse
Genetic constraint (gnomAD): Loss-of-function variants: 17 observed, 46.51 expected, observed/expected ratio (o/e) 0.37, 90% interval 0.25 to 0.55. The upper end of that interval is the gene's LOEUF score, 0.55, which puts it in group 2 of 6, group 1 being the genes least tolerant of losing a copy. Missense variants: 508 observed, 711.55 expected, observed/expected ratio (o/e) 0.71, 90% interval 0.66 to 0.77. Synonymous variants: 198 observed, 242.87 expected, observed/expected ratio (o/e) 0.82, 90% interval 0.73 to 0.92.
Homologues: Paralogues in human: POTEF (99% identical), POTEI (97% identical), POTEJ (94% identical), POTEB3 (47% identical), POTED (46% identical), POTEB (44% identical), POTEB2 (44% identical), POTEC (44% identical), POTEH (43% identical), POTEG (43% identical), POTEM (42% identical), POTEA (34% identical), and 2 more.
Diseases named in the same sentence as POTEE in open-access papers:
POTEE is named in the same sentence as 11 diseases in open-access papers, as found by Europe PMC text mining. Sharing a sentence is not in itself a finding about the gene and the disease. The quoted sentences say what the papers report.
breast carcinoma (3 papers, 2019 to 2023). "Here we identify POTEE (POTE Ankyrin domain family member E) as a novel Rac1-SUMO1 effector involved in breast cancer malignancy that controls invadopodium formation through the activation of Rac1-SUMO1." (PMID 38098337, 2023). "We found that the co-localization of POTEE with Rac1 is correlated with more aggressive breast cancer subtypes." (PMID 38098337, 2023). "Based on omics-based whole-genome transcriptome and whole-proteomic profiling, researchers observed that POTEE was closely related to breast cancer and might be involved in disease progression." (PMID 31723122, 2019).
colorectal cancer (2 papers, 2019 to 2021). A primary or metastatic malignant neoplasm that affects the colon or rectum. "(2019) suggest that POTEE paralog promotes colorectal cancer by upregulating the SPHK1/p65 signaling pathway." (PMID 34788504, 2021). "We firstly examined endogenous expression of POTEE in 11 colorectal cancer cell lines by qRT-PCR and western blot analysis." (PMID 31723122, 2019). "Together, these data indicated that POTEE is upregulated in human CRC tissues and overexpression of POTEE correlates with malignant phenotypes as well as unfavorable prognosis of colorectal cancer." (PMID 31723122, 2019). "Altogether, our findings suggested a POTEE/SPHK1/p65 signaling axis could promote colorectal tumorigenesis and POTEE might potentially serve as a novel biomarker for the diagnosis and an intervention of colorectal cancer." (PMID 31723122, 2019).
ovarian carcinoma (2 papers, 2016 to 2021). A malignant neoplasm originating from the surface ovarian epithelium. "Recent studies have discerned that POTEE paralog gets epigenetically regulated in many cancers including ovarian cancer." (PMID 34788504, 2021). "This evidence suggests that since the majority of the network associators of POTEE are epigenetically activated in many cancers, it is quite natural for POTEE paralog to get over-expressed and epigenetically regulated in ovarian cancer too." (PMID 34788504, 2021). "Since the majority of the network associators of POTEE are epigenetically activated in many cancers as they have been reported in the literature, it is quite natural for POTEE paralog to get over-expressed and epigenetically regulated in ovarian cancer too." (PMID 34788504, 2021). "With all these studies in hand, we aim to identify the lesser-known POTEE paralog in ovarian cancer using an exploratory in silico pipeline." (PMID 34788504, 2021). "Despite expression in normal tissues of the prostate, ovary, testis, and placenta (hence the acronym POTE), transcripts of POTEE gene are also detected in tissues of prostate, breast, lung, colon, and ovarian cancers." (PMID 28018022, 2016). "Thus, it is quite natural for POTEE paralog too to get over-expressed and epigenetically regulated in cancer and to be specific, ovarian cancer." (PMID 34788504, 2021). "Finally, to establish why POTEE paralog showcases an epigenetic nature in ovarian cancer, we adopt a network based epigenetic approach that lists out the highly significant, direct and physical associators of POTEE." (PMID 34788504, 2021).
cancers of the colon (1 paper, 2015). "POTEE (POTE ankyrin domain family, member E) is a newly identified cancer-testis antigen that has been found to be expressed in a wide variety of human cancers including cancers of the colon, prostate, lung, breast, ovary, and pancreas." (PMID 25860145, 2015).
colorectal tumor (1 paper, 2019). "Consistent with mRNA level, the protein expression analyzed by western blot and immunohistochemistry (IHC) also verified the elevated expression of POTEE in colorectal tumor tissues." (PMID 31723122, 2019). "Here we show that POTEE, which was identified as a member E of POTE ankyrin domain family, was significantly upregulated in colorectal tumors and predicted poor overall survival of CRC patients." (PMID 31723122, 2019).
hepatocellular carcinoma (1 paper, 2024). A malignant tumor that arises from hepatocytes. "This study aimed to investigate the role of microtubule-affinity regulatory protein kinase 1 (MARK1) in hepatocellular carcinoma (HCC) progression, its association with sorafenib sensitivity, and the interplay between MARK1 and POTE Ankyrin domain family member E(POTEE) in HCC cells." (PMID 39534429, 2024).
prostate carcinoma (1 paper, 2019). A carcinoma that arises from epithelial cells of the prostate gland. "Furthermore, recent findings indicated the roles of POTEF, one of homologous protein of POTEE, in the regulation of apoptosis in prostate cancer cells." (PMID 31723122, 2019).
rectal cancer (1 paper, 2019). A primary or metastatic malignant neoplasm that affects the rectum. "External dataset also validated that high POTEE mRNA level could also predicted significantly poorer overall survival in GSE87211 with 189 rectal cancer patients involved." (PMID 31723122, 2019).
cancer (8 papers, 2014 to 2024). A tumor composed of atypical neoplastic, often pleomorphic cells that invade other tissues. "Up to date, few previous studies reported an association between POTEE and cancer prognosis because POTEE is a newly identified CT antigen." (PMID 25860145, 2015). "Given its role in tumor dissemination, the leading cause of cancer-related deaths, POTEE could represent a potential therapeutic target for these types of cancer." (PMID 38098337, 2023). "In this study, a large number of clinical samples of HCC patients for the first time were used to investigate the role of MARK1 and POTEE in the development of this cancer." (PMID 39534429, 2024). "Among members, POTEE is a dominant subtype that is expressed in many types of cancers and established cancer cell lines." (PMID 34136404, 2021). "Despite the possible oncogenic roles of POTEE in different cancer types, its expression pattern, functions, mechanism largely remain obscure and need further study." (PMID 31723122, 2019). "Higher ICI-4W expression of extracellular matrix (ECM) genes, including trypsinogens (PRSS1 and PRSS2) and matrix metalloproteases, and genes encoding cancer antigens (CTAG2, SAGE1, MAGEA1/A4/A10, POTEE, and PRAME) was significantly associated with ICI resistance and tumor growth during ICI-4W." (PMID 37433281, 2023). "POTEE, a dominant subtype expressed in many cancers and cancer cell lines." (PMID 25860145, 2015). "POTEE (POTE ankyrin domain family, member E) is a newly identified cancer testis antigen expressed in normal testis, ovary, and placenta, and in many cancers, including those of the prostate, colon, lung, breast, ovary, and pancreas." (PMID 25860145, 2015). "We found a reduction in MARK1 expression and an increase in POTEE expression in HCC tissues in comparison to the adjacent ones, suggesting that MARK1 may serve as a tumor suppressor gene in this cancer." (PMID 39534429, 2024). "All these recent studies suggest that POTEE paralog gets epigenetically activated in different cancers, however, there is no significant data available to prove its epigenetic association in terms of network-based epigenetic interactor analyses." (PMID 34788504, 2021). "While three of the chimeras (ACTB->POTEM, ACTB->POTEE and SP100->HMGB1) have been found in normal population, three of the chimeras (C2orf27A->NBEA, HILPDA->EFCAB3, FARSB->TRIM61) were previously identified only in cancer samples." (PMID 25133550, 2014).
tumor (4 papers, 2019 to 2024). "Specifically, the mRNA and protein expression of POTEE were significantly upregulated in human CRC tumor samples and cell lines." (PMID 31723122, 2019). "POTEE silence significantly inhibited cell proliferation in the tumor sections as determined by Ki67 staining." (PMID 31723122, 2019). "In CRC cells, POTEE could act as an oncogene and could promote cell growth, cell-cycle progression, inhibit apoptosis, and elevates xenograft tumor growth." (PMID 31723122, 2019). "POTEE activates Rac1 in the invadopodium by recruiting TRIO-GEF (triple functional domain protein), and it induces tumor cell proliferation and metastasis in vitro and in vivo." (PMID 38098337, 2023).
POTEE also shares sentences with these, for which no sentence is quoted: non-small cell lung carcinoma (1 paper).